NINJ1 (ninjurin 1)
Diseases named in the same sentence as NINJ1 in open-access papers (continued):
Sharing a sentence is not in itself a finding about the gene and the disease.
ischemic stroke (2 papers, 2025 to 2026). A stroke disorder caused by obstruction of blood flow to the brain, due to thrombotic (local blood clot formation) or embolic (due to a blood clot or other material traveling from another site) event. "Therapeutic interventions targeting NINJ1—such as intranasal siRNA delivery or peptides targeting its N-NAM—have shown anti-inflammatory effects in models of ischemic stroke and systemic inflammation." (PMID 40075648, 2025). "NINJ1 also plays a critical role in inflammatory conditions, including multiple sclerosis, experimental autoimmune encephalomyelitis, and ischemic stroke." (PMID 40075648, 2025).
non-small cell lung carcinoma (2 papers, 2022 to 2025). A group of at least three distinct histological types of lung cancer, including non-small cell squamous cell carcinoma, adenocarcinoma, and large cell carcinoma. "For example, NINJ1 has been shown to promote the formation and progression of non-small cell lung cancer (NSCLC) by protecting cancer stem cells from hostile microenvironments via the ligand-independent activation of the LRP6/β-catenin signaling pathway." (PMID 40075648, 2025).
peripheral nerve injury (2 papers, 2016 to 2025). Injury to a peripheral nerve. "For instance, NINJ1 was identified as a transcript strongly upregulated after peripheral nerve injury." (PMID 27417541, 2016). "Nerve injury-induced protein 1 (Ninjurin-1, NINJ1) was initially discovered as an adhesion molecule upregulated in Schwann cells after peripheral nerve injury." (PMID 39979243, 2025).
prostate carcinoma (2 papers, 2024 to 2025). A carcinoma that arises from epithelial cells of the prostate gland. "Conversely, NINJ1 expression is significantly elevated in CTCs from patients with locally advanced prostate cancer, where its overexpression promotes prostate cancer cell migration and invasion in vitro." (PMID 40075648, 2025).
rheumatoid arthritis (2 papers, 2019 to 2022). A chronic, systemic autoimmune disorder characterized by inflammation in the synovial membranes and articular surfaces. "Furthermore, high NINJ1 expression is associated with human bone disorders, such as rheumatoid arthritis and postmenopausal osteoporosis." (PMID 30700695, 2019). "Gene expression profiles of 10 patients with osteoarthritis (OA) and 9 with rheumatoid arthritis (RA) demonstrated significantly elevated NINJ1 expression in RA (1.99-fold compared with OA)." (PMID 30700695, 2019).
Salmonella Infections (2 papers, 2023 to 2025). Infections with bacteria of the genus SALMONELLA. "Collectively, these data imply a critical role for NINJ1 in contributing to IL-1 release and cell death during Salmonella infection in human macrophages." (PMID 40162563, 2025). "While Salmonella infection induced equivalent caspase-1 activation in untreated and muscimol-treated cells, the formation of punctate ninjurin-1 speck-like assemblies was blocked by muscimol." (PMID 37798443, 2023). "Salmonella infection led to ninjurin-1 redistribution into punctate speck-like assemblies (middle row), consistent with oligomers observed by native electrophoresis-based Western blot." (PMID 37798443, 2023).
Stroke (2 papers, 2023 to 2026). Sudden impairment of blood flow to a part of the brain due to occlusion or rupture of an artery to the brain. "We detail the molecular logic of this axis-from GPR68's sensing of pathological acidosis (pH ≤ 6.4) and shear stress to NINJ1's oligomerization and DAMP release-and explore its potential role in unifying the pathophysiology of diverse disorders like TBI, stroke, MS, and AD." (PMID 41969524, 2026).
viral pneumonia (2 papers, 2025 to 2026). Inflammation of the lung parenchyma that is caused by a viral infection. "NINJ1 also has potential as a bioindicator of disease severity and prognosis in viral pneumonia and viral sepsis, suggesting the lipid-peroxidation–NINJ1–DAMP axis is relevant to human pathophysiology." (PMID 41518848, 2026). "In summary, our study offers insights into the role of NINJ1 in immunopathology during IAV infection and reveals its potential as a therapeutic target and bioindicator in viral pneumonia and viral sepsis." (PMID 40983621, 2025). "Collectively, our findings indicate a pivotal role of NINJ1 in the immunopathology of IAV infection and its potential as a bioindicator of disease severity and prognosis in viral pneumonia and viral sepsis." (PMID 40983621, 2025). "Several in vivo studies have revealed the potential role of NINJ1 in different diseases, but no studies have investigated viral pneumonia." (PMID 40983621, 2025). "However, little is known about the role of NINJ1 in IAV-induced PANoptosis and viral pneumonia." (PMID 40983621, 2025).
acute pancreatitis (1 paper, 2025). An acute inflammatory process that leads to necrosis of the pancreatic parenchyma.
alcoholic hepatitis (1 paper, 2022). Acute hepatitis resulting from ingestion of alcohol. "As regards human data, hepatitis B virus‐associated ALF (GSE38941) and alcoholic hepatitis (GSE28619) patients exhibited significant increases in Ninj1 expression in liver tissues as compared with normal controls." (PMID 36071453, 2022).
atrial fibrillation (1 paper, 2022). A disorder characterized by an electrocardiographic finding of a supraventricular arrhythmia characterized by the replacement of consistent P waves by rapid oscillations or fibrillatory waves that vary in size, shape and timing and are accompanied by an irregular ventricular response. "However, the role of plasma Ninj1 in atrial fibrillation (AF) has not been reported." (PMID 35392805, 2022).
Autoimmunity (1 paper, 2020). The occurrence of an immune reaction against the organism's own cells or tissues. "Transcriptome group 3 (ACVRL1, CD93, CEBPB, NINJ1, SRGN) encodes preferentially for proteins related to autoimmunity." (PMID 32325790, 2020).
brucellosis (1 paper, 2024). Brucellosis is a bacterial infection that spreads from animals to people via unpasteurized dairy products or by exposure to contaminated animal products or infected animals. "As the major contributor of potential inflammatory storm, many inflammatory response genes (e.g., ITGB2, OSM, FPR1, CEBPB, NINJ1) and canonical pro‐inflammatory cytokines (e.g., CXCL8, CCL3, CCL4, TNF, IL1B, S100A12) were expressed at higher levels in brucellosis patients than in healthy donors." (PMID 39135683, 2024).
carotid artery thrombosis (1 paper, 2023). Blood clot formation in any part of the carotid arteries. "Furthermore, we performed a FeCl3-induced carotid artery thrombosis model to explore the role of NINJ1 in thrombosis." (PMID 36835580, 2023).
coronary artery disease (1 paper, 2025). "The soluble form of NINJ1 is an antiatherogenic protein, and its plasma levels are elevated in patients with coronary artery disease (CAD) and are associated with the occurrence of CAD and the severity of coronary stenosis." (PMID 39958360, 2025).
coronary stenosis (1 paper, 2025). Narrowing of the coronary artery lumen diameter. "Clinical studies have demonstrated that serum NINJ1 levels are significantly elevated in patients with coronary atherosclerotic heart disease and are associated with the severity of coronary stenosis, serving as an independent risk factor for cardiovascular disease." (PMID 40356625, 2025).
endometriosis (1 paper, 2021). The growth of functional endometrial tissue in anatomic sites outside the uterine body. "Ninj1 is a novel neurotransmitter and, along with other activities, it appears to enhance the innervation under the known inflammatory conditions that are present in endometriosis lesions." (PMID 33435569, 2021).
endotoxemia (1 paper, 2023). "Nevertheless, Wt and NINJ1 deficient mice display equal sensitivity to LPS-induced endotoxemia, another model of pyroptosis-driven inflammatory pathology, thereby questioning the general importance of DAMPs release to an inflammatory phenotype." (PMID 37980412, 2023).
glioma (1 paper, 2019). A benign or malignant brain and spinal cord tumor that arises from glial cells (astrocytes, oligodendrocytes, ependymal cells). "The control shRNA virus (“sh-C”) failed to inhibit Ninj1/2 expression and glioma cell functions." (PMID 31794427, 2019).
Left atrial enlargement (1 paper, 2022). Increase in size of the left atrium. "Plasma Ninj1 was positively correlated with left atrial enlargement and thromboembolic risk in AF patients." (PMID 35392805, 2022). "Plasma Ninj1 levels were elevated in patients with AF, associated with left atrial enlargement and thromboembolic risk in AF." (PMID 35392805, 2022).
leprosy (1 paper, 2022). Leprosy is a chronic infectious disease affecting primarily the skin and peripheral nervous system. "For example, polymorphisms in certain genes such as IL10, ninjurin 1 and TNF have been associated with leprosy susceptibility." (PMID 35492305, 2022).
liposarcoma (1 paper, 2024). A usually painless malignant tumor that arises from adipose tissue. "Thus, it is reasonable that NINJ1 may be a good prognostic factor for liposarcomas." (PMID 38733554, 2024).
liver diseases (1 paper, 2022). "Nevertheless, little is known about the function of Ninj1 during the development of liver diseases." (PMID 36071453, 2022). "However, the roles of Ninj1 during the pathogenesis of liver diseases and the mechanisms responsible are still unknown." (PMID 36071453, 2022).
lymphoma (1 paper, 2023). A malignant (clonal) proliferation of B- lymphocytes or T- lymphocytes which involves the lymph nodes, bone marrow and/or extranodal sites. "In contrast, at higher doses (50 μM) of APR-246, NINJ1 loss caused a reduction in LDH release from both the wt and BAX/BAK deficient lymphoma cells, consistent with both cell types undergoing a lytic form of cell death under these conditions." (PMID 36739334, 2023). "Western blotting confirmed reduced NINJ1 expression in the parental and BAX/BAK double knockout Eμ-Myc lymphoma cells that had been transduced with the Ninj1 specific sgRNA." (PMID 36739334, 2023). "Little LDH release was seen in the BAX/BAK double knockout lymphoma cells at the relatively low dose of APR-246, regardless of whether they expressed or lacked NINJ1, because these cells are resistant to this treatment." (PMID 36739334, 2023).
melanoma (1 paper, 2024). A malignant, usually aggressive tumor composed of atypical, neoplastic melanocytes. "For example, CASP4, NLRP1, MEFV, IL18, and NINJ1 correlated positively with GSDMD in metastatic melanoma patients but not in primary melanoma patients." (PMID 38229080, 2024).
Obesity (1 paper, 2015). Accumulation of substantial excess body fat. "An SNP in the first of those genes, NINJ1, has been shown to be associated with severe obesity in children." (PMID 25953783, 2015).
ocular hypertension (1 paper, 2023). Abnormally high intraocular pressure. "Ninj1 was enriched in several inflammatory, leukocyte migration, and chemotaxis-related pathways in the scRNA-seq data used in our studies, suggesting that Ninj1 plays a role in immune cell recruitment and the subsequent inflammatory damage in injury pathogenesis brought on by ocular hypertension." (PMID 37029422, 2023).
osteosarcoma (1 paper, 2024). A usually aggressive malignant bone-forming mesenchymal neoplasm, predominantly affecting adolescents and young adults. "We further collected a series of osteosarcoma cell lines with varying mRNA levels of NINJ1, and measured their PMR rate under high strain." (PMID 39483869, 2024).
pancreatitis (1 paper, 2023). Inflammation of the pancreas. "The study aims to obtain a deeper understanding of the involvement of Ca2+ and NINJ1 in the inflammatory process of pancreatitis, providing scientific evidence for the development of novel therapeutic strategies for SAP." (PMID 37511311, 2023).
postmenopausal osteoporosis (1 paper, 2019). Metabolic disorder associated with fractures of the femoral neck, vertebrae, and distal forearm. "Finally, high NINJ1 expression is correlated with human bone disorders, such as RA and postmenopausal osteoporosis." (PMID 30700695, 2019).
rectum adenocarcinoma (1 paper, 2024). An adenocarcinoma arising from the rectum. "Our analysis revealed a significant positive correlation between NINJ1 expression and these two ferroptosis markers in the prostate and rectum adenocarcinoma." (PMID 39424803, 2024).
relapsing-remitting MS (1 paper, 2026). "Here, we identify Ninjurin-1 as a marker and regulator of immune activation and CNS infiltration in relapsing-remitting experimental autoimmune encephalomyelitis (RR-EAE), a model of relapsing-remitting MS (RRMS)." (PMID 42064092, 2026).
stenosis (1 paper, 2025). "Furthermore, NINJ1 and MMP9 are independent risk factors for plaque enhancement, arterial stenosis, and positive vascular remodeling." (PMID 40356625, 2025).
Thrombocytopenia (1 paper, 2025). A reduction in the number of circulating thrombocytes. "Future studies to dissect the functional relevance of NINJ1 in ANKRD26 mutation-associated thrombocytopenia could shed new light on its broader implications for other hematological and inflammatory disorders." (PMID 40170493, 2025).
Thromboembolism (1 paper, 2022). The formation of a blood clot inside a blood vessel that subsequently travels through the blood stream from the site where it formed to another location in the body, generally leading to vascular occlusion at the distant site. "We further evaluated the correlation of plasma Ninj1 levels with CHA2DS2-VASc and HAS-BLED scores in patients with AF, which are recognized as risk assessment criteria for thromboembolism and bleeding, respectively." (PMID 35392805, 2022). "Plasma Ninj1 was positively correlated with LAVI and CHA2DS2-VASc score, which are crucial parameters of atrial remodeling and thromboembolism, respectively." (PMID 35392805, 2022).
triple-negative breast carcinoma (1 paper, 2019). An invasive breast carcinoma which is negative for expression of estrogen receptor (ER), progesterone receptor (PR), and human epidermal growth factor receptor 2 (HER2). "Considering its role as a c-Jun-regulated antiapoptotic gene, apoptosis was induced by Ninj1 downregulation in triple-negative breast cancer cells and further accelerated by TNF-α, whereas Ninj1 overexpression ameliorated TNF-α-induced apoptosis in c-Jun knockdown cells." (PMID 30700695, 2019).
type 2 diabetes (1 paper, 2019). "Accordingly, NINJ1 is associated with insulin insensitivity and type 2 diabetes incidence in African Americans61." (PMID 30700695, 2019).
viral infection (1 paper, 2025). "Although NINJ1 was first reported as a mediator of PMR 4 years ago, little effort had been made to explore NINJ1’s role in viral infection prior to this study." (PMID 40983621, 2025). "Since little is known about the expression pattern of NINJ1 during viral infection, we first determined the transcript level in IAV-infected murine lungs." (PMID 40983621, 2025). "Further studies exploring NINJ1 in other viral infections and in other cell types are warranted." (PMID 40983621, 2025).
infection (14 papers, 2013 to 2026). The state of being infected such as from the introduction of a foreign agent such as serum, vaccine, antigenic substance or organism. "Although we observe initial differences in replication shortly after infection, Ninj1-deficiency has consequences for all stages of the HSV-1 lifecycle and eventually results in higher production of infectious viral particles." (PMID 41261285, 2026). "Card19lxcn mice were more susceptible to infection with Yersinia, exhibiting enhanced mortality and systemic bacterial burdens relative to wildtype mice, implicating NINJ1-mediated lysis in host-pathogen interactions." (PMID 34648590, 2021). "Here, we report that Ninj1-deficiency in mouse macrophages leads to enhanced infection with HSV-1." (PMID 41261285, 2026). "However, Ninj1−/− mice being more susceptible to infection with C.rodentium and wild-type (WT) BMDMs releasing proinflammatory cytokines would suggest an overall pro-inflammatory role for NINJ1." (PMID 37664463, 2023). "Although all abnormally developed Ninj1-/- mice were excluded we cannot rule out other potential abnormities, which do not manifest in appearance but might directly or indirectly affect susceptibility to infection." (PMID 40983621, 2025). "Further exploring the effects of Ninj1-deficiency, we find that HSV-1 entry of Ninj1–/– macrophages is enhanced, with a higher infection rate and more viral particles entering each cell on average." (PMID 41261285, 2026). "Together, this indicates that during infection of mouse macrophages, NINJ1 reduces HSV-1 entry, which alters the inflammatory potential of macrophages." (PMID 41261285, 2026). "We examined NINJ1 expression globally in the three groups and found that NINJ1 was profoundly elevated after infection and was most abundantly expressed in the deceased group." (PMID 40983621, 2025). "Wild-type (WT) THP-1 monocyte-derived macrophages were treated with control scrambled siRNA or siRNA targeting NINJ1 for 72 hr prior to infection." (PMID 40162563, 2025). "The expression of Ninj1 tended to increase after infection, and the increase in expression was more pronounced when infected with a lethal dose, which indicated its possible association with disease severity." (PMID 40983621, 2025). "As an adhesion molecule, Ninj1 reportedly regulates macrophage function in endotoxin-mediated inflammation and is engaged in the immune responses triggered by cellular infection or stress." (PMID 37029422, 2023). "Similar effects of NINJ1 have been confirmed in infection conditions and heat stress." (PMID 39958360, 2025). "Notably, in addition to the more commonly studied areas such as neurological diseases, tumors, inflammatory diseases, and vascular damage, the role of NINJ1-mediated PMR in infection is difficult to determine." (PMID 39958360, 2025). "The NINJ1 filament represents an elegant biophysical mechanism of cellular disintegration, and knowledge of its atomic structure opens opportunities for therapeutic interventions in cancer, infection and inflammatory diseases." (PMID 37198476, 2023). "However, we observe that infected Ninj1-deficient cells do not die more or earlier than WT controls at early timepoints in infection, at which we already observe a difference in infection rates." (PMID 41261285, 2026). "In addition to regulating the inflammatory phenotype of cells, Ninj1 actively mediates the rupture of the plasma membrane and regulates the programmed death of inflammatory cells, thereby participating in the host defense against exogenous infection." (PMID 42004242, 2026). "Here we describe how Ninjurin1 (NINJ1) controls HSV-1 infection of macrophages, a key cell type that protects mice against infection." (PMID 41261285, 2026). "Murine Ninj1−/− and Gsdmd−/− bone-marrow derived macrophages (BMDMs) released less lactate dehydrogenase (LDH), a surrogate marker for cell death, upon stimulation with LPS, nigericin or infection with different bacterial pathogens." (PMID 37664463, 2023).